CYB5B (cytochrome b5 type B)
Description:
Cytochrome b5 is a membrane-bound hemoprotein functioning as an electron carrier for several membrane-bound oxygenases.
Synonyms: OMB5; CYB5-M; CYPB5M
Tractability: Small molecule: a structure with a bound ligand is known. Antibody: UniProt predicts a signal peptide or a membrane-spanning region. PROTAC: ubiquitination databases record sites on it; its protein half-life has been measured.
Gene: Protein-coding gene on chromosome 16 (69,398,402 to 69,466,264, forward strand). Ensembl gene ENSG00000103018.
Subcellular location: Mitochondrion outer membrane
Subcellular location (Human Protein Atlas): Endoplasmic reticulum; Centriolar satellite; Cytosol
Pathways (Reactome):
Metabolism: Phase I - Functionalization of compounds; Sphingolipid de novo biosynthesis; eNOS activation
Gene Ontology:
Molecular function: heme binding; nitrite reductase (NO-forming) activity; protein binding
Biological process: nitric oxide biosynthetic process; response to oxidative stress; xenobiotic metabolic process
Cellular component: membrane; nitric-oxide synthase complex; endoplasmic reticulum membrane; mitochondrial outer membrane
Genetic constraint (gnomAD): Loss-of-function variants: 9 observed, 14.38 expected, observed/expected ratio (o/e) 0.63, 90% interval 0.38 to 1.09. The upper end of that interval is the gene's LOEUF score, 1.09, which puts it in group 4 of 6, group 1 being the genes least tolerant of losing a copy. Missense variants: 89 observed, 112.77 expected, observed/expected ratio (o/e) 0.79, 90% interval 0.66 to 0.94. Synonymous variants: 41 observed, 38.38 expected, observed/expected ratio (o/e) 1.07, 90% interval 0.83 to 1.39.
Homologues: Orthologues: chimpanzee CYB5B (100% identical), guinea pig CYB5B (82% identical), macaque CYB5B (81% identical), pig CYB5B (80% identical), rabbit CYB5B (79% identical), mouse Cyb5b (73% identical), dog CYB5B (68% identical), rat Cyb5b (61% identical), tropical clawed frog cyb5b (55% identical), zebrafish cyb5b (52% identical), Caenorhabditis elegans cytb-5.1 (37% identical), Drosophila melanogaster CG3566 (35% identical). Paralogues in human: CYB5A (45% identical).
Diseases named in the same sentence as CYB5B in open-access papers:
CYB5B is named in the same sentence as 10 diseases in open-access papers, as found by Europe PMC text mining. Sharing a sentence is not in itself a finding about the gene and the disease. The quoted sentences say what the papers report.
Hodgkins lymphoma (2 papers, 2010 to 2024). A heterogeneous group of malignant lymphoid neoplasms of B-cell origin characterized histologically by the presence of Hodgkin and Reed-Sternberg (HRS) cells in the vast majority of cases. "Additionally, CYB5B overexpression has been identified in HodgkinLymphoma and aggressive Non-Hodgkin Lymphomas, further underscoring its linkto mitochondria and immune response." (PMID 39076954, 2024).
Allergy (1 paper, 2021). An allergy is an immune response or reaction to substances that are usually not harmful. "Pathways related to intracellular signalling pathway, stress response, VEGF and MTOR related, the latter showed in the last years to be related with allergy; and oxidative phosphorylation are up-regulated, like FOXP1, SERPIN family, SOD2, caspase family, PGF, CYB5B, SERP1 and SLC25A4." (PMID 34784380, 2021).
breast carcinoma (1 paper, 2024). "Metabolic proteins including aldehyde dehydrogenase 1 family member A3, L-lactate dehydrogenase B chain, cytochrome b5 type B and elongation factor Tu, and elongation factor 1δ were overexpressed in the breast cancer cells and prostate cancer cells." (PMID 38249992, 2024).
lymphoma (1 paper, 2010). A malignant (clonal) proliferation of B- lymphocytes or T- lymphocytes which involves the lymph nodes, bone marrow and/or extranodal sites. "Toxicity, therefore, might be minimal if anti-CYB5B antibodies are used for targeted therapy of CYB5B surface positive lymphomas." (PMID 20100355, 2010). "When we checked the CYB5B gene in HL cells for mutations that might lengthen the hydrophobic domain we found none, thus this explanation does not appear to hold true in human lymphoma cells." (PMID 20100355, 2010). "We have now identified the 21 kDa protein as CYB5B which is expressed on the plasma membrane of lymphoma cells but not normal lymphocytes, reactive lymphocytes or bone marrow precursor cells." (PMID 20100355, 2010).
cancer (3 papers, 2011 to 2025). A tumor composed of atypical neoplastic, often pleomorphic cells that invade other tissues. "The protein levels of SEC11A and CYB5B were significantly increased in cancer tissues." (PMID 35573741, 2022). "For example, CD44, ARIH2, CSDE1 (also known as UNR), CYB5B, SF3B1, and RCN2, which have been reported to be overexpressed in cancer, showed an increased proportion of shorter 3′-UTRs, primarily as a result of alternative cleavage and polyadenylation (APA)." (PMID 40702779, 2025).
CYB5B also shares sentences with these, for which no sentence is quoted: non-Hodgkin lymphoma (2 papers); anaplastic large cell lymphoma (1); diabetes (1); diabetic retinopathy (1); prostate carcinoma (1).